TREM1 (triggering receptor expressed on myeloid cells 1)
Diseases named in the same sentence as TREM1 in open-access papers (continued):
Sharing a sentence is not in itself a finding about the gene and the disease.
infection (continued). "Taken together with the PIZSA score, these results suggest that TREM-1 might have a higher affinity for the E2 NSP4 protein, which could lead to different infection outcomes or virulence, although in vitro analysis conducted with different viral strains is required to fully investigate this." (PMID 41156639, 2025). "In addition, 15 STSS survivors demonstrated declining levels of plasma TREM-1 over 72 h after infection, whereas 3 non-survivors either displayed extremely high levels or increased sharply of TREM-1 in plasma." (PMID 37456011, 2023). "A neutrophil with low TREM-1 expression may not perform its function correctly and thus favor the spread of the parasite and secondary infections." (PMID 35402286, 2022). "Furthermore, infection with hepatitis C virus and the human immunodeficiency virus (HIV), or even exposure to the HIV proteins Tat or gp120 without infection, induces the expression of TREM-1." (PMID 34960790, 2021). "About a 10% of Trem1+/+ mice survived the infection while none of the Trem1−/− survived." (PMID 33525982, 2021). "The effect of dexamethasone could possibly be extrapolated to infections by other Gram-negative bacteria since down-regulation of TREM-1/sTREM-1 was also shown when LPS was used to stimulate U937 cells." (PMID 24350219, 2013). "While the levels of TREM1 are found up-regulated during the course of the disease we found a negative correlation for SYT13 and IL1F10 which implicate that their downregulation during the course of infection may negatively impact the host response to infection." (PMID 38283341, 2023). "In addition, the highly induced CPs (P < .0001) at 2 h post-infection were Neuroinflammation Signaling, TLRs, PPRs, IL-6, and NF-kB Signaling; while at 24 h, the highly induced CPs (P < .0001) were TLRs, Neuroinflammation Signaling, PPRs, IL6, and TREM1 Signaling." (PMID 33382951, 2021). "However, in contrast to the clinical scores, there was a decrease in TREM-1 expression at both levels at 3 day post-infection (P<0.01), whereas no change was detected in either TREM-1 expression levels or the clinical score data between the two groups at 5 days post-infection." (PMID 25464008, 2014). "At 48 h of infection, Mtb ΔRD1 infection did not significantly upregulate IFN, TREM1 and TNFR2 signalling, and there were fewer dysregulated genes in immune pathways after Mtb ΔRD1 infection when compared to Mtb WT." (PMID 32938685, 2020). "We found that TREM1 was moderately induced by Mtb infection and it was synergistically induced by 25(OH)D3 and co-treatment with PBA, irrespective of infection." (PMID 26133770, 2015). "At 3 days post infection with 5×106 CFU of L. pneumophila, CFU and neutrophil numbers in the BALF did not significantly differ between Trem1+/+ and Trem1−/− mice." (PMID 24453980, 2014). "However, increased plasma concentrations of TREM-1 have also been reported in patients with the systemic inflammatory response syndrome secondary to cardiac surgery with CPB and after cardiac arrest, without infection." (PMID 24289157, 2013). "However, other studies have reported that TREM-1 expression increases in noninfectious pathologies, and our previous results have shown that the expression of this molecule increases after surgery, particularly in patients with preexisting SIRS, but without infection." (PMID 19442309, 2009).
tumor (115 papers, 2009 to 2026). "Beyond its role in acute and chronic inflammatory processes, TREM-1 is also involved in cancer emergence and progression probably by alteration of the tumor-associated neutrophils (TAN) and macrophages (TAM)." (PMID 41785288, 2026). "Our findings indicate that TREM-1 activation shifts tumor-associated macrophages (TAMs) and tumor-associated neutrophils (TANs) toward a pro-inflammatory state, promoting antitumor immune responses." (PMID 40917508, 2025). "Such a TREM1+ TME facilitates tumor cells to acquire hallmark capabilities of cancer including sustained proliferative signaling, invasion, metastasis and immune evasion." (PMID 39744496, 2025). "Altogether, our results indicate that TREM-1 activation reprograms tumor-associated myeloid cells from an immunosuppressive to a pro-inflammatory phenotype, promoting anti-tumor immune responses." (PMID 40917508, 2025). "In cancer, pharmacological blockade of TREM-1 is a promising approach to target tumor-associated macrophages (TAM), the major innate immune cells that infiltrate solid tumors and can form up to 50% of the tumor mass." (PMID 41404075, 2025). "Together, these data provide the first experimental in vivo evidence that inhibitor specificity and treatment timing can significantly impact the anti-tumor effect of TREM-1-mediated modulation of the innate immune response caused by cancer therapy." (PMID 41404075, 2025). "Our work identifies BIT as a spatially-localized NF-κB-driven tumor epithelial resistance state associated with TREM1-myeloid dominated inflammation characterized by high levels of cytokines IL1 and OSM." (PMID 39289380, 2024). "Our spatial neighborhood analysis describes the full range of tumor-immune dynamics within a naïve epithelial carcinoma, from anti-tumor immune storm to pro-tumor TREM1-associated BIT and stroma-independent BST." (PMID 39289380, 2024). "Prominently, elevated levels of TREM1 in macrophage-infected human malignancies, in conjunction with reduced levels of spontaneous TREM1 conformation, have been linked to tumor aggressiveness, recurrence, and inadequate patient survival." (PMID 39149674, 2024). "Specifically, tumor-associated TREM1 myeloid cells define the specialized inflammatory environment in which BIT tumor epithelium arises." (PMID 39289380, 2024). "In the liver, tissues exposed to heat stress, the upregulated pathways comprised of IL-17 signaling, NOD1/2 signaling associated with liver injury, TREM1 signaling of hepatic inflammation, tumor microenvironment signaling, Th1 signaling, and eNOS signaling." (PMID 38719902, 2024). "TREM1 participated in the immunosuppressive response, correlated with tumor-associated immune cells and synergistic with several immunosuppressive members." (PMID 38370418, 2024). "BST and BIT occur in adjacent but distinct regions of a single tumor: BST arises within the core tumor nodule, while BIT emerges from a specialized inflammatory environment defined by a tumor-associated TREM1 myeloid signature." (PMID 39289380, 2024). "Tumor-infiltrating MDSCs harvested from TREM1-deficient mice exhibited diminished suppressive capacity on the proliferation of CD3+ T cells activated with anti-CD3/anti-CD28 compared with their TREM1-positive counterparts." (PMID 37651197, 2023). "Collectively, these data suggested that TREM1 deficiency limits tumor progression by reconditioning the myeloid infiltrate in the TME via reduced accumulation and immunosuppressive capacity of macrophages and MDSCs." (PMID 37651197, 2023). "Overall, our findings suggest that TREM1 deficiency leads to a considerable reconditioning of the tumor-myeloid landscape by inhibiting macrophage recruitment." (PMID 37651197, 2023). "Together, our results highlight that TREM1 expression is associated with various human carcinomas and plays a critical role in modulating tumor immune infiltrates, making it a candidate for therapeutic intervention." (PMID 37651197, 2023).
tumor (continued). "We next examined the association between TREM1 expression and overall survival by utilizing the Cox regression model on the various tumor types." (PMID 37651197, 2023). "The triggering receptor expressed on myeloid cell 1 (TREM1) plays a critical role in development of chronic inflammatory disorders and the inflamed tumor microenvironment (TME) associated with most solid tumors." (PMID 37651197, 2023). "Trem1 on myeloid cells is associated with tumor progression and poor prognosis, and the blockade of this receptor on TAMs is able to ameliorate immunosuppression and revert ICI resistance." (PMID 36555441, 2022). "They demonstrated that TREM-1 was found in HCC cancer cells and tumor tissues and that high TREM-1 was significantly associated with higher recurrence and lower survival in HCC patients." (PMID 35875168, 2022). "Growing evidence suggests TREM-1 involvement in oncogenesis through cancer-associated inflammation and the tumor microenvironment (TME)." (PMID 35875168, 2022). "They demonstrated that peritumoral TREM-1 expression was significantly associated with vascular invasion (p < 0.001), tumor size (p = 0.001) and high TNM stage (p < 0.001)." (PMID 35875168, 2022). "Of these, ADM, DCBLD2, EREG, ITGA5, MIF, MMP14, and TREM1 were associated with poor prognosis and significantly increased in tumor, while BTG2 was related to favorable prognosis and decreased in tumor." (PMID 35002712, 2021). "This difference in rank was also significant for the TNBC and ER+ subtypes alone (P=0.007, two-group comparison), where higher TREM1 frequency associated with TNBC status while lower TREM1 frequency associated with ER-positive tumor status." (PMID 34956864, 2021). "To address this possibility more conclusively, we used mRNA expression data for 72 normal renal epithelial cells and 531 clear cell RCC tumors from the TCGA database to assess the expression changes and possible association of tumor Trem1 to patient outcomes." (PMID 35223446, 2021). "In tumors, TREM1 seems to be induced on tumor-associated macrophages, which has been correlated with cancer recurrence and poor survival." (PMID 33575478, 2021). "TREM-1 deficiency also reduced the number of tumor-infiltrating neutrophils in both models, with alterations observed in cytokine and chemokine profiles." (PMID 34956864, 2021). "Taken together these data demonstrate that patients with RCC have increased levels of sTREM-1 in their blood compared with healthy donors and that tumor-associated Trem1 correlates with high disease stage, primary tumor size, and poor outcomes in RCC." (PMID 35223446, 2021). "TREM-1 expression was described on TAMs (tumor-associated macrophages (TAMs)) and was also associated with shorter survival in other cancer types." (PMID 32684831, 2020). "In non-small cell lung cancer (NSCLC) patients, TREM-1 expression in TAMs was associated with tumour recurrence and poor survival." (PMID 32908142, 2020). "In murine models, the tumor-promoting function of TREM-1 was associated with augmented expression of several pro-inflammatory mediators and increased compensatory proliferation of parenchymal cells." (PMID 29093489, 2017). "While the precise mechanisms behind TREM-1-mediated tumor development still need to be deciphered, our findings show that intratumoral expression of Trem1 associates with increased expression of pro-inflammatory genes implicated in intestinal tumorigenesis." (PMID 29093489, 2017). "Here, using an inflammation-driven model of CRC and mice genetically deficient in Trem1, we have established a clear role for TREM-1 in intestinal tumorigenesis, demonstrating that Trem1−/− mice show significantly reduced tumor development." (PMID 29093489, 2017). "In order to investigate the underlying mechanisms behind TREM-1-driven tumor development, H&E stained sections of Trem1+/+ and Trem1−/− tumors were at first assessed for the tumor grade." (PMID 29093489, 2017).
tumor (continued). "High expression levels of TREM-1 were reported to be associated with tumor recurrence and poor prognosis of patients with NSCLC." (PMID 27244892, 2016). "Immunohistochemistry and immunoflorescent staining from the lung tumors demonstrated that TREM-1–positive cells are tumor associated macrophages." (PMID 24842612, 2014). "Collectively, these data suggest that TREM-1 expression is upregulated in tumor associated macrophages in non-small cell human lung cancer." (PMID 24842612, 2014). "We next wanted to define the mechanism by which PGE2 mediates the expression of TREM-1 in tumor associated macrophages." (PMID 24842612, 2014). "Collectively these data show that the expression of TREM-1 in tumor associated macrophages which is induced by PGE2 is mediated through EP2 and EP4 receptors and is driven by an increase in the level of cAMP." (PMID 24842612, 2014). "Interestingly, current research has shown that TREM1 is expressed on tumor-associated macrophages (TAMs), dendritic cells (DCs), cancer-associated fibroblasts (CAFs) and tumor-infiltrating neutrophils within the TME." (PMID 39744496, 2025). "Furthermore, correlation analyses between TREM1 and tumor mutational burden (TMB) and microsatellite instability (MSI) in pan-cancer were conducted." (PMID 39744496, 2025). "In addition, we found that TREM1 expression was strongly linked with tumor-infiltrating immunological cells using a series of bioinformatics data from public platforms." (PMID 39744496, 2025). "Additionally, immune analysis revealed that TREM1 was robustly positively associated with tumor-associated macrophages (TAMs) and regulatory T cells (Tregs) infiltrating." (PMID 39744496, 2025). "TREM-1 has been linked to proinflammatory responses and facilitating tumour progression." (PMID 39684475, 2024). "While we commonly observe TREM2-associated proliferative BCC and BST in human and murine BCCs, the variable abundance of BIT cells in BCC patients and murine tumors argues for a specialized role of the TREM1-associated inflammation in driving high levels of NF-κB signaling in tumor epithelium." (PMID 39289380, 2024). "Activating monocyte/neutrophil TREM1 with the agonistic antibody PY159 (IgG1) enhances co-stimulatory molecule expression and IFNγ responses to support anti-tumour immunity, but TREM1 is also associated with poor prognosis and inflammation-related carcinogenesis." (PMID 38831013, 2024). "In addition, among the tumor-infiltrating lymphocytes (TILs), TREM1 deficiency led to significant attenuation in exhausted CD8+ T (T Exh) cells (CD8+Tim-3+CTLA-4+) while increasing the proportion of cytotoxic CD8+ T (T Cyt) cells (CD8+GzmB+CD25+)." (PMID 37651197, 2023). "Next, we characterized the impact of TREM1 deficiency on MDSC populations within tumor infiltrates." (PMID 37651197, 2023). "Simultaneous expansion of tumor-infiltrating neutrophils in the same treatment groups suggest a previously unknown mechanism by which TREM1 deficiency drives neutrophil-dependent expansion of UTCαβ antitumorigenic immunity and warrants further research." (PMID 37651197, 2023). "TREM1 deficiency and antagonism restrain tumor growth by modifying tumor immune infiltrates." (PMID 37651197, 2023). "We analyzed whether ApoE and/or TREM-1 expression is associated with tumor development in lung tumor patients." (PMID 31275318, 2019). "However, a recent study showed that expression levels of TREM-1 in tumor associated macrophages and blood monocytes were significantly decreased during lung tumor progression." (PMID 31275318, 2019). "Together these data suggest that TREM-1 may be a critical link in the tumor microenvironment between tumor-associated macrophage activation, inflammatory response, and cancer progression." (PMID 24842612, 2014). "We hypothesized that TREM-1 activation in tumor associated macrophages may be induced by PGE2 generated by cyclo-oxygenase-2 from tumor cells." (PMID 24842612, 2014).
tumor (continued). "Most importantly, immune cell infiltration analysis revealed that TREM1 expression was closely linked to the infiltration of Tregs and tumor-associated macrophages, which may contribute to create a tumor immunosuppressive microenvironment and favor tumor progression." (PMID 39744496, 2025). "Therefore, we adopted the ESTIMATE and TIMER algorithms to investigate the infiltration of immune cells and found that TREM-1 expression is associated with tumor-infiltrating immune cells, and exhibited positive associations with immune infiltration of dendritic cells, neutrophils and CD8+T cells." (PMID 34122331, 2021). "Recently, experimental and human studies have suggested that TREM-1 pharmacologic targeting may represent a potential novel therapeutic modality to inhibit MP-mediated chronic inflammation-associated tumor development, pointing to TREM-1 as an attractive new immunotherapeutic target also for cancer." (PMID 32456204, 2020). "Thus, the expression and functional significance of TREM-1 on cells of the monocyte/macrophage lineage seems to depend on the tissue-dependent context or the nature of tumor-associated inflammation and calls for further investigation across distinct types of cancer." (PMID 29093489, 2017). "Since our results indicated that the decreasing TREM-1 expression on TAMs in tumor tissue is associated with cancer metastases and tumor progression in the advanced stage, we expected that the lower levels of TREM-1 on TAMs might be a promising prognostic biomarker." (PMID 27244892, 2016). "However, in tumors or more likely in tumor-associated macrophages according to our results, TREM1 may also be induced by hypoxia." (PMID 19536297, 2009). "Another study demonstrated that the TREM1 agonist PY159 activated tumor myeloid cells, promoting a pro-inflammatory TME34." (PMID 41413734, 2025). "We observed that TREM-1 activation within the PDAC TME led to a significant reduction in tumor growth." (PMID 40917508, 2025). "TREM1 signaling promotes the production of inflammatory cytokines and fusogenic proteins, favoring tumor progression, heterogeneity, and resistance to treatment." (PMID 40868137, 2025). "A pan-cancer analysis reveals TREM1+ PMN-MDSCs as key mediators of immunosuppression by remodeling the tumor microenvironment, highlighting TREM1 as a therapeutic target." (PMID 41413734, 2025). "TREM1 downregulation alters the proportions of M1 macrophages and Tregs in the tumor tissue from our HCC xenograft model." (PMID 40551711, 2025). "Instead, the proportion of Treg cells in tumor tissues in which TREM1 was downregulated was significantly lower." (PMID 40551711, 2025). "In summary, these findings indicate that combination of chemotherapy with broad (pan-TREM-1) or macrophage-restricted TREM-1 blockade yielded a significant synergistic anti-tumor effect compared to chemotherapy alone." (PMID 41404075, 2025). "Over a 60-day period, only 1 out of 6 mice implanted with TREM1 KO LCSLCs developed tumors, whereas in the TREM1-positive implants, tumor formation was significantly higher, with 4 out of 6 developing tumors." (PMID 40677705, 2025). "To further validate the relationship between TREM1 expression and prognosis of OV, we firstly performed RT-qPCR to compare the mRNA expression levels of TREM1 in tumor and normal tissues from clinical samples." (PMID 39744496, 2025). "By employing both CRISPR-Cas9-mediated KO and the small molecule inhibitor VJDT, we demonstrated that TREM1 inhibition significantly reduces tumor size, depletes the number of LCSLCs, and impairs spheroid formation." (PMID 40677705, 2025). "This staining exhibited marked overlap between TREM1 and α-fetoprotein, a classical marker for HCC cells, indicating that the tumor cells themselves are positive for TREM1." (PMID 40677705, 2025). "Chemically, VJDT is a substituted 2,3,3a,4,7,7a-hexahydro-4,7-(epiminocarbonyl)isoindole analog, employed to assess the effects of TREM-1 inhibition on tumor progression." (PMID 41226426, 2025).